SEPTIN1 (septin 1)
Description:
Filament-forming cytoskeletal GTPase (By similarity). May play a role in cytokinesis (Potential).
Synonyms: DIFF6; PNUTL3; SEPT1; Septin-1; LARP; SEP1
Tractability: PROTAC: ubiquitination databases record sites on it.
Gene: Protein-coding gene on chromosome 16 (30,378,135 to 30,395,991, reverse strand). Ensembl gene ENSG00000180096.
Subcellular location: Cytoplasm; Cytoplasm, cytoskeleton; Cytoplasm, cytoskeleton, microtubule organizing center, centrosome; Midbody
Subcellular location (Human Protein Atlas): Actin filaments
Gene Ontology:
Molecular function: identical protein binding; protein binding; GTPase activity; molecular adaptor activity; GTP binding
Biological process: cytoskeleton-dependent cytokinesis; intracellular protein localization; regulation of exocytosis
Cellular component: midbody; cell division site; microtubule cytoskeleton; septin complex; septin ring; synaptic vesicle; centrosome; cytoplasm; cytoskeleton; meiotic spindle
Genetic constraint (gnomAD): Loss-of-function variants: 46 observed, 44.27 expected, observed/expected ratio (o/e) 1.04, 90% interval 0.82 to 1.33. The upper end of that interval is the gene's LOEUF score, 1.33, which puts it in group 5 of 6, group 1 being the genes least tolerant of losing a copy. Missense variants: 416 observed, 451.46 expected, observed/expected ratio (o/e) 0.92, 90% interval 0.85 to 1. Synonymous variants: 188 observed, 175 expected, observed/expected ratio (o/e) 1.07, 90% interval 0.95 to 1.21.
Homologues: Orthologues: chimpanzee SEPTIN1 (100% identical), pig SEPTIN1 (95% identical), dog SEPTIN1 (95% identical), mouse Septin1 (94% identical), rat Septin1 (94% identical), guinea pig SEPTIN1 (91% identical), rabbit SEPTIN1 (65% identical), Drosophila melanogaster Septin1 (51% identical), Drosophila melanogaster Septin2 (37% identical), Caenorhabditis elegans unc-61 (35% identical). Paralogues in human: SEPTIN5 (61% identical), SEPTIN2 (55% identical), SEPTIN7 (49% identical), SEPTIN3 (39% identical), SEPTIN6 (37% identical), SEPTIN9 (37% identical), SEPTIN11 (37% identical), SEPTIN14 (37% identical), SEPTIN10 (36% identical), SEPTIN8 (36% identical), SEPTIN12 (36% identical), TMEM250 (9% identical).
Diseases named in the same sentence as SEPTIN1 in open-access papers:
SEPTIN1 is named in the same sentence as 15 diseases in open-access papers, as found by Europe PMC text mining. Sharing a sentence is not in itself a finding about the gene and the disease. The quoted sentences say what the papers report.
viral infection (1 paper, 2021). "The link viral infection-septin is not straightforward: some septins have an anti-viral effect (septin 1/2/7/9/11), while others exhibit pro-viral properties (septin 3/10)." (PMID 33801245, 2021).
SEPTIN1 also shares sentences with these, for which no sentence is quoted: Alzheimer disease (2 papers); breast carcinoma (2); Parkinson disease (2); tumor (2); cancer (1); Cirrhosis (1); infection (1); invasive breast carcinoma (1); melanoma (1); mood disorder (1); oral squamous cell carcinoma (1); psychosis (1); schizophrenia (1); squamous cell carcinoma (1).